WAS (WASP actin nucleation promoting factor)
Diseases named in the same sentence as WAS in open-access papers (continued):
Sharing a sentence is not in itself a finding about the gene and the disease.
Nance-Horan syndrome (1 paper, 2015). A syndrome characterized by the association in male patients of congenital cataracts with microcornea, dental anomalies and facial dysmorphism. "We considered an X-linked recessive model (female child less severe than male) and identified variants were inNHS (Nance-Horan syndrome),DDX53, WAS, andTREX2; four variants inRPGR." (PMID 26535115, 2015).
nephritis (1 paper, 2021). Inflammation of renal tissue. "Consistent with the B6.Nba2 and WAS models, T1IFN signaling was also not required for TLR7-driven nephritis in NZM2328 lupus-prone mice, although we observed a moderate reduction in TLR7-mediated autoimmune B cell responses, immune complex deposition, and nephritis in B6.Sle1b mice." (PMID 34638804, 2021).
rectal adenocarcinoma (1 paper, 2018).
renal carcinoma (1 paper, 2023). A carcinoma arising from the epithelium of the renal parenchyma or the renal pelvis. "Furthermore, we assessed the transcription expression of WAS in renal cancer tissues, various renal carcinoma cell lines and human renal tubular cells (HK2) using quantitative polymerase chain reaction (qPCR)." (PMID 37122750, 2023).
Wilson disease (1 paper, 2025). A very rare inherited multisystemic disease presenting non-specific neurological, hepatic, psychiatric or osseo-muscular manifestations due to excessive copper deposition in the body. "In one confirmed case of Wilson Disease (site 1 case 2), WASP 274 level was also below cutoff and subsequent sequencing of WAS gene showed a variant of uncertain significance, c.133-38C>A." (PMID 39846592, 2025).
X-linked disease (1 paper, 2021). X-linked form of disease. "This X-linked disease is caused by mutation in the WAS gene encoding the WAS protein (WASp), an actin cytoskeleton regulator." (PMID 32935622, 2021).
tumor (33 papers, 2015 to 2025). "In summary, these data suggested that CAF cluster 6 was closely associated with tumour development and WAS more likely to interact with cells in the left colon (including both normal tissue and tumours)." (PMID 39294858, 2024). "Of these, mutations in the WAS gene encoding WASp have been extensively studied and revealed the importance for actin cytoskeleton dynamics in tumor surveillance by cytotoxic cells." (PMID 33240268, 2020). "Similarly, it was shown that WAS deficiency increases tumor susceptibility and accelerates tumor growth." (PMID 38688902, 2024). "Elevated expression level of FYN (p value = 0.000), LCP2 (p value = 0.002), PTPRC (p value = 0.011), WAS (p value = 0.005), ZAP70 (p values = 0.000) and NCF4 (p values = 0.047) were associated with tumor size." (PMID 34834481, 2021). "Oncogenes show specific activity in tumor cells, with LMO2, LYN, TNFRSF17, CARD11, and BCL7A being active in Tumor B1, while BCL2 and WAS are specifically active in Tumor B2." (PMID 41238550, 2025). "In this study, using RNA-seq data of 576 HCC patients, a panel of seven genes (including LCP2, TYROBP, ZAP70, PTPRC, FYN, WAS and NCF4) has been identified which are independent predictors of delayed tumor recurrence and improved patient prognosis." (PMID 34834481, 2021). "Since we were not able to obtain tumor tissue from WAS patients, we next wanted to examine if we could correlate expression of WASp and IL-2 with tumor outcome in cancer patients." (PMID 27477778, 2016).
infection (31 papers, 2008 to 2025). The state of being infected such as from the introduction of a foreign agent such as serum, vaccine, antigenic substance or organism. "Viral clearance and associated immunopathology were measured after infection of WASP-deficient (WAS KO) mice with lymphocytic choriomeningitis virus (LCMV)." (PMID 23141740, 2013). "Also, cases with WAS mutation were primarily manifested infection (44.4%)." (PMID 36544766, 2022). "A significant difference in cytokine secretion was observed between infected WT and WAS KO BMDCs at 3 and 5 h post-infection (hpi) and this effect was further enhanced in response to LPS priming." (PMID 29146903, 2017). "We compared the kinetics of autophagy in EPEC-infected WT and WAS KO BMDCs by studying LC3-I/LC3-II expression during infection." (PMID 29146903, 2017). "T cells were collected at day 6 after infection when antigen-specific cell numbers were equivalent between WAS KO and C57BL/6 mice." (PMID 23141740, 2013). "WAS patients may have a wide variety of infections due to the impact of WASP on multiple blood cell lineages." (PMID 33717203, 2021). "These defects may be responsible for the inability of WAS B cells in reaching the site of infection and get properly activated." (PMID 28512459, 2017). "Thus, the effect of a fairly short delay in phosphorylation of LAT or WAS, for example, could potentially have a major impact on the number of antigen-specific T cells responding to an infection." (PMID 25147952, 2014). "A statistically significant increase in percentage of ASC specks (exposed to 3 h LPS followed by 3 h infection), and FLICA (caspase-1 active) and propidium iodide (PI) double-positive (pyroptotic) cells in WT vs. WAS KO BMDCs was also recorded." (PMID 29146903, 2017). "We analyzed the expression of IL-7R on GP33 and NP396 tetramer–positive cells at day 8 after infection and found fewer IL-7R+ virus–specific CD8+ T cells in WAS KO mice." (PMID 23141740, 2013). "As LPS alone showed no differential effect on LDH release between WT and WAS KO BMDCs, we focused on the effect of infection alone on cell death." (PMID 29146903, 2017). "However, on days 12 and 20 after infection, the numbers of total and virus-specific CD8+ T cells recovered from blood was markedly reduced in WAS KO mice, whereas at that time, LCMV had been eliminated in C57BL/6 mice." (PMID 23141740, 2013). "Six days after infection, the total number of CD8+ T cells and LCMV-specific, GP33 tetramer–positive CD8+ T cells in the spleen, liver, and blood was similar between C57BL/6 and WAS KO mice." (PMID 23141740, 2013). "Microglial actins in astrocyte-co-cultures were down-regulated after HIV-1/VSV infection and the proteins related to actin binding, polymerization and stability, including MARCKS, moesin, Wiskott-Aldrich syndrome protein (WAS) and gelsolin, were all up-regulated." (PMID 18575609, 2008). "Patients with severe WAS (especially those who do not express WASP) typically have a life expectancy of <15 years in the absence of HSCT due to hemorrhage, malignancy and severe infection." (PMID 33717203, 2021).
cancer (28 papers, 2012 to 2025). A tumor composed of atypical neoplastic, often pleomorphic cells that invade other tissues. "In our model, exon 2 of HYAL2 exhibited a higher inclusion ratio in WASP-KO-iMPs, which might be related to the high cancer susceptibility in WAS patients." (PMID 35752626, 2022). "WAS protein level was found highly expressed in cancer tissues, particularly within renal tumor cells via the human protein atlas (HPA)." (PMID 37122750, 2023). "In support of these observations, a CCLE (Cancer Cell Line Encyclopedia) analysis predicted high expression of WAS and WIP in FLI1-positive hematological malignancies." (PMID 33717090, 2021). "Genes differing insignificantly from healthy tissue were IMP-3, CDH1, IQGAP1, NEDD9, TKS5, WAS and ARPC4, indicating minimal alterations in their expression levels in the analyzed cancer samples." (PMID 37623256, 2023). "It is notable that the top genes from an overall cancer vs control comparison included GATA4, CCDC88B, and WAS." (PMID 35202405, 2022). "However, there was no thorough paper about ITGB2-AS1, except that ITGB2-AS1 was reported to have high co-expression with multiple cancer genes (IKZF1, LCK, and WAS)." (PMID 29941860, 2018). "In addition to the negative regulation of TCR signaling, knockout of WAS could also activate PLK1 signaling, which has been suggested to serve as oncogenic signaling in most human cancers." (PMID 30619485, 2018).
genetic disorders (5 papers, 2017 to 2025). "WAS is a rare genetic disorder that affects the immune system caused by mutations in the WAS gene on the X chromosome." (PMID 39917307, 2025).
WAS also shares sentences with these, for which no sentence is quoted: breast carcinoma (9 papers); COVID-19 (4); hematological malignancies (4); melanoma (4); T cell lymphoma (4); eosinophilia (3); inflammatory bowel disease (3); myelodysplastic syndrome (3); pancreatic cancer (3); vasculitis (3); acute myeloid leukemia (2); anaplastic large cell lymphoma (2); bacterial infections (2); Chronic colitis (2); chronic granulomatous disease (2); chronic mucocutaneous candidiasis (2); chronic myeloid leukemia (2); diffuse large B-cell lymphoma (2); fungal infections (2); glioma (2); glomerulonephritis (2); Idiopathic Thrombocytopenic Purpura (2); lymphopenia (2); osteopetrosis (2); platelet disorders (2); renal disease (2); Sepsis (2); severe combined immunodeficiency (2); tetanus (2); acute lymphoblastic leukemia (1).
A further 81 diseases each share a sentence with WAS in 1 paper.